BCR (BCR activator of RhoGEF and GTPase)
Diseases named in the same sentence as BCR in open-access papers (continued):
Sharing a sentence is not in itself a finding about the gene and the disease.
leukemia (continued). "Interestingly, FISH analysis of patient 4 revealed that, in addition to the founding chromosome 21 amplification, this leukaemia harboured a BCR-ABL translocation." (PMID 41291054, 2025). "To understand whether OSM is functionally relevant for the disease progression of leukemia, we used Osm-deficient mice or WT mice as BM donors in models of FLT3-ITD- and BCR::ABL1-positive leukemia." (PMID 41372120, 2025). "Thus, the study of BCR/ABL-independent features unique to mutant leukemia cells would be a particularly potential strategy for CML therapy." (PMID 40346054, 2025). "However, the constitutive activation of Abl by the disruption of its autoinhibition mediated by the translocation to a variety of many genes such as BCR, Tel, and ETV6 is the main cause of the development of different tumor types, including leukemia." (PMID 39123481, 2024). "It has been demonstrated that BCR signaling is constitutively active in CLL patients, leading to BTK being associated with the development of CLL, making it an important drug target in this type of leukemia very common in the Western world." (PMID 38845697, 2024). "Identification of the BCR::ABL1 transcript in CML entailed the discovery of molecular alterations as point mutations, fusion proteins and splice variants in other BCR::ABL1-negative leukemias." (PMID 39104388, 2024). "Moreover, we performed homing assays in IL-17A-/- mice to detect the effect of IL-17A knockout on the homing of leukemia cells by using CFSE-labeled leukemia cells isolated from BCR-ABLtTA mice." (PMID 38172124, 2024). "However, resistance to ABL TKIs can develop in CML patients due to BCR::ABL1 point mutations and CML leukemia stem cell (LSC)." (PMID 38714583, 2024). "In addition, a study employing primitive CD34+CD38− leukemia initiating cells (LICs) from CML patients showed that OM can effectively kill BCR–ABL+ LICs in vitro." (PMID 38704602, 2024). "Loss of ABL1 autoregulation contributes to the constitutive activation of BCR::ABL1, driven by homo-oligomerisation of BCR::ABL1 mediated by the coiled-coil domain of the breakpoint cluster region (BCR) protein, which in turn induces uncontrolled proliferation and survival of leukemia stem cells." (PMID 38965368, 2024). "After treatment with dasatinib and VMCP, leukemia recurred with positive BCR-ABL." (PMID 38450181, 2024). "Previous publications on BCR::ABL1-positive leukemia have primarily focused on the Major form of the translocation due to technical challenges in determining breakpoints in the substantially larger minor BCR region (~ 2.9 vs. ~71.5 kbp)." (PMID 38970095, 2024). "However, previous Ph+ leukemia models were unable to generate reciprocal ABL1::BCR fusion in combination with BCR::ABL1 fusion." (PMID 35999358, 2023). "The translocation generating BCR::ABL1 that drives Ph+ tumors such as SUP-B15 is described as able to induce leukemia onset and development by itself, and Ph+ tumors tend to express simple karyotypes, being overly dependent on BCR::ABL1 expression, a condition denominated “oncogene addiction”." (PMID 38067214, 2023). "Overall, we identified a new signaling axis “BCR-ABL-TAL1-TSPAN32-PTEN-PI3K-AKT” in Ph+ leukemias." (PMID 36854750, 2023). "Furthermore, it has recently been observed that the remaining genomic fragments were imperfectly reassembled, generating random fusions while maintaining the leukemia-initiating BCR::ABL1 fusion." (PMID 37296693, 2023). "Treatment and understanding of BCR::ABL1-positive leukaemias is a precision medicine success story." (PMID 38550948, 2023). "Our work shows that a comprehensive molecular analysis might be necessary to characterize leukemias more likely to correspond to AMLs with the BCR::ABL1 WHO (World Health Organization) entity." (PMID 37895120, 2023). "Although the fusion gene has been extensively studied in the pathogenesis of leukemia, the function of BCR and whether it is a potential trigger to other tumors and diseases are not clear yet." (PMID 37730603, 2023).
leukemia (continued). "Finally, the control and Zfx-overexpressing BaF3 cells and BaF3–BCR/ABL cells were injected into lethally irradiated mice, and Kaplan–Meier analysis showed that Zfx overexpression significantly accelerated BCR/ABL-induced leukemia." (PMID 37864206, 2023). "Taken together, these results suggest that pterostilbene may hold potential for the treatment of BCR/ABL+ leukemia, in particular for those showing ABL-dependent TKI resistance." (PMID 35027628, 2022). "Collectively, pterostilbene administration may be a novel noninvasive treatment option for patients with BCR/ABL+ leukemia, especially for those resistant or intolerant to TKIs." (PMID 35027628, 2022). "Several studies have addressed elevated expression levels of GPR34 in malignancies, including cervical cancer, metastatic melanoma, MALT lymphoma, BCR/ABL-positive leukemia, gastric cancer, and colon cancer, as well as its essential roles in tumor development and progression." (PMID 34997428, 2022). "Due to many structural similarities between these identified fusion oncogenes, the results described in this study may be applicable to additional leukemias driven by BCR fusion proteins." (PMID 35574218, 2022). "First, we found that 4 successive 2-day apart intravenous injections of T2 combo at a fixed dose (TPEN 5 mg/kg: TPGS 100 mg/kg) showed a statistically significant reduction of Ba/F3 BCR-ABL leukemia cells (– 69%) in leukemia BALB/c mice compared to untreated leukemia group." (PMID 36352172, 2022). "In addition to the general chemotherapy agents, targeted therapies are used for specific leukaemias, such as tyrosine kinase inhibitors (e.g., Imatinib), which are used for BCR/ABL positive leukaemia." (PMID 33802972, 2021). "Using strategies that target YBX3 or pre-BCR-related modules in pre-BCRd-related leukemias may also further improve outcomes in patients with these subsets of high-risk B-ALL." (PMID 34824268, 2021). "In conclusion, MeST has been able to suppress the growth of leukemia cells harboring BCR/ABL." (PMID 34068907, 2021). "We will study the effects of the methanol extract of Sphagneticola trilobata (L.)Pruski (Asteraceae) (MeST) on the growth of leukemia cells that may contain the BCR/ABL gene." (PMID 34068907, 2021). "Based on these findings, we hypothesize that ZINC21710815 may decrease leukemia cell proliferation by decreasing the phosphorylation of BCR-ABL, STAT5, and Crkl." (PMID 33748144, 2021). "For instance, tyrosine kinase inhibitors (TKIs) are used to treat leukemia with a BCR-ABL fusion gene, and abnormally spliced mRNA precursors after BCR-ABL transcription are often found that lack the target domain of TKIs and allow tumor cells to escape killing by drugs." (PMID 34249669, 2021). "We used imatinib, a small molecule tyrosine kinase inhibitor that was originally developed to inhibit the BCR-ABL fusion protein in leukemia but also inhibits c-Kit, PDGF receptors, and CSF1R and is being investigated as a possible chemotherapy for metastatic melanoma." (PMID 32450888, 2020). "An in vitro cell homing assay was used in which we measured the percentage of BCR-ABL leukemia cells migrating from the donor chamber of a transwell culture through a semi-permeable membrane to the bottom chamber containing either media or hMSC with or without 1,25(OH)2VD3 conditioning." (PMID 32047189, 2020). "This is surprising, as this form of BCR-ABL is a well-characterized cancer fusion in leukemia." (PMID 31965184, 2020). "Our data define STAT5B as major STAT5 isoform driving BCR/ABL+ leukemia." (PMID 30679796, 2019). "CD27 signaling promotes the growth of BCR/ABL+ leukemia cells by activating the Wnt pathway." (PMID 31074387, 2019). "To compare tissue oxygenation and T cell dynamics in healthy BM to that in BM with acute lymphoblastic leukemia (ALL), we infused the immune competent CD2-DsRed/CD11c-YFP dual fluorescent mice with syngeneic cyan-fluorescent leukemia cells transformed by the BCR-Abl fusion protein expression." (PMID 30885258, 2019).
leukemia (continued). "To test whether the effect extends to human BCR/ABL+ leukemia, we ablated STAT5A or STAT5B via shRNA-mediated knockdowns in K562 cells." (PMID 30679796, 2019). "Therefore, they also assessed the clonogenic potential of pre-BCR+ and pre-BCR− mouse leukaemia cells in the presence of an LCK inhibitor (A-770041) or SYK inhibitor (P505-15)." (PMID 28819864, 2018). "Some therapeutically-targetable leukemia antigens originate from oncogenesis itself and are leukemia cell-specific, such as the BCR/ABL1 fusion protein in CML and Philadelphia (Ph)+ ALL, PML/RAR-α in acute promyelocytic leukemia, FLT3-ITD and mutated NPM1 in AML and IDH1/2." (PMID 29466292, 2018). "Leukaemia blasts (pre-BCR+ ALL) can thus hijack the pre-BCR signalling pathway to induce differentiation arrest and avoid clonal extinction, and reactivating this pathway may be an attractive therapeutic target (as reviewed in Ref." (PMID 28819864, 2018). "Here, we introduce such a workflow and demonstrate its utility for cellular drug-response monitoring of BCR-ABL tyrosine kinase inhibitors in K562 leukemia cells: First, low-molecular mass features indicating drug responses are computationally extracted from groups of MALDI-TOF mass spectra." (PMID 30050068, 2018). "In contrast, mutant isoforms of BCR-ABL1 carrying inactivating mutations in the SH1 domain, or mutants lacking the BCR coiled coil domain, did not induce leukemia." (PMID 29455643, 2018). "BCR function has been essentially described in the context of BCR‐ABL‐transformed leukaemia." (PMID 29438985, 2018). "A variety of breakpoints in BCR and ABL1 rearrangements generate BCR-ABL1 chimeric proteins with different domain compositions, of which the three major variants (p185, p210, and p230) occur in different types of leukemia." (PMID 30040819, 2018). "In the leukemia characterized by BCR/ABL and MLL fusion gene, the expression of HOX was elevated." (PMID 29383189, 2017). "The SFKs intracellular non-receptor tyrosine kinases are collaborative oncogenic kinases in BCR/ABL-induced leukemia and may act to couple BCR/ABL to certain downstream signaling pathways involved in leukemic transformation." (PMID 29312576, 2017). "Interestingly, the majority of MLL breakpoints identified in infant leukemias lie toward the 3’ end of the BCR, similar to those seen in leukemias secondary to treatment with topoisomerase II inhibitors." (PMID 28232907, 2017). "Collectively our data provides first evidence that gadd45a functions as a suppressor of BCR/ABL driven leukemia and may provide a novel prognostic marker of CML progression." (PMID 28086219, 2017). "A more profound understanding for the cytokine environment of leukemic cells and for the function of SOCS1 as an oncogene or as a tumor suppressor in BCR-ABL mediated transformation might be required to completely eradicate leukemia-initiating cells." (PMID 28753604, 2017). "Here, we studied the individual roles of PAK1 and PAK2 in BCR/ABL1+ leukaemia." (PMID 28707321, 2017). "Furthermore, impairment of NFAT activity facilitates leukemia cell elimination by the BCR-ABL inhibitor dasatinib, and NFAT inhibition augments the anti-cancer effects of vemurafenib and trametinib in melanoma." (PMID 28881766, 2017). "This novel mechanism of action makes oridonin efficacious against Ph+ leukemia cells regardless of the BCR-ABL mutation status." (PMID 28128329, 2017). "Therefore, the molecular dissection of BCR-ABL signaling network is advisable to identify the signaling axes which are essential for the maintenance of Ph+ leukemias and whose inhibition allows to achieve synthetic lethality together with BCR-ABL TKIs." (PMID 27563822, 2016). "Similarly, BIM protein increased eight-fold upon RAS inactivation and three-fold upon BCR-ABL inactivation in the Eμ -tTA/TRE-RAS and Eμ-tTA/TRE-BCR-ABL leukemia, respectively." (PMID 27095570, 2016).
leukemia (continued). "That pre-BCR+ leukemic cells are arrested at the pre-B stage is supported by animal models, where aberrant signaling downstream of the pre-BCR gives rise to spontaneous leukemia." (PMID 27611867, 2016). "This could be related to a more “physiological” level of BCR-ABL expression in de novo generated human primitive leukemia cells that could be insufficient to enable their engraftment." (PMID 26561938, 2015). "Because IGF-IR is dispensable for the activity of HSCs but regulates BCR/ABL leukemia cell fates and supports self-renewal of CML cells, targeting IGF-IR may be an ideal anti-leukemia strategy." (PMID 25648584, 2015). "We therefore sought to investigate whether BCR/ABL-OOF and BCR/ABL could synergize in leukemia cells." (PMID 26682280, 2015). "It was reported that combined treatment with nilotinib or dasatinib with SGX393 (inhibitor of native and T315I-mutant BCR/ABL) might be useful for reduction of BCR/ABL mutants in Ph-chromosome-positive leukemia." (PMID 24634785, 2014). "Collectively, the drug combinations and methods we describe might be a first step towards more effective interventions for leukemia patients, especially those with the BCR-ABL translocation." (PMID 25029499, 2014). "However, only the leukemia cell lines harboring Ph chromosome with constitutively active BCR-ABL (marked red) show a strong phosphorylation of LASP1 at tyrosine-171." (PMID 24913448, 2014). "The human K562 leukemia cell line expresses a constitutively active BCR-ABL tyrosine kinase." (PMID 24595334, 2014). "Thus, the unmutated prototypic CLL69 ancestors selected from the primary BCR repertoire of umbilical cord Fab library were similar to those of CLL69C expressed by leukemia B cells." (PMID 23840319, 2013). "The introduction of the BCR-ABL TKIs in CML therapy has been a major advance in leukemia treatment." (PMID 23460890, 2013). "Of note, STAT5 is also a critical node in the signaling pathway of BCR/ABL, and we have recently learned from the model of BCR/ABL-tumour initiation that its activity may influence the ultimate leukaemia phenotype." (PMID 22852088, 2012). "Nearly all patients with CML express the BCR-ABL fusion product on their leukemia cells." (PMID 23241263, 2012). "Therefore, BCR/ABL-positive leukemia cells become genetically unstable by including B-NHEJ in DNA DSB repair." (PMID 21637496, 2010). "For example, the efficacy of imatinib (Gleevec) in the treatment of leukaemias bearing the BCR-ABL fusion provides one clinical example of oncogene addiction and how it may be exploited therapeutically." (PMID 19357772, 2009). "We investigated whether the cell lines A-5 and A-21, isolated from mice that had developed leukemia while on Nilotinib treatment, had BCR/ABL gene amplification as compared to the parental cell line 8093." (PMID 17958915, 2007). "It is established that in CML patients, DC can not only present the leukemia specific BCR-ABL peptides, but also that such presentation can lead to generation of antigen-specific T-cells capable of inducing lysis of CD34 cells from CML but not control patients in an MHC-I dependent manner." (PMID 17254347, 2007). "Imatinib mesylate, competitive inhibitors of certain tyrosine kinases including the intracellular kinases ABL and BCR-ABL fusion proteins present in some leukemia's, and platelet-derived growth factor receptors, is the first effective drug in the treatment of metastatic GIST." (PMID 15713236, 2005). "Additionally, the presence of the BCR::ABL1 fusion supports the classification of this leukemia as MPAL (T/myeloid) with a defined genetic abnormality, in accordance with the World Health Organization (WHO), fifth edition, and the International Consensus Classification (ICC)." (PMID 40605863, 2025).
leukemia (continued). "In addition, the disruption of neddylation could not only induce apoptosis of the leukemic cells with BCR-ABL mutations, but also eradicate leukemia stem cells (LSCs), strongly suggesting the advantageous outcomes of targeting this neddylation processes." (PMID 38741123, 2024). "With the proviso you have a sensitive and specific assay, cell-free detection of ctDNA in solid cancers might be less susceptible to Poisson noise than other MRD-testing assays that rely on presence of intact cancer cells in a sample (e.g. detection of BCR::ABL1 transcripts in leukaemia cells)." (PMID 38637690, 2024). "This may be due to the complex nature of chemotherapy resistance in BCR::ABL1pos leukemias." (PMID 38001691, 2023). "Thus, the treatment of BA inhibitor in Bcr-Abl-expressing HL60 cells induces the degradation of BCR-ABL, which may re-sensitize leukemia cells expressing the BCR-ABL to chemotherapy." (PMID 36139353, 2022). "This hypothesis was initially suggested based on differences between the normal B cell repertoire and that of CLL deduced from studies of many leukemic clones, indicating the selection of certain BcR specificities, capable of favoring leukemia clonal expansion." (PMID 36430731, 2022). "Thus, the development of new therapeutic strategies for BCR/ABL+ leukemias is still important." (PMID 35027628, 2022). "However, the incidence of BCR/ABL-positive samples far exceeds that of the associated leukemias, suggesting that the presence of the BCR/ABL fusion gene alone is insufficient to trigger leukemia." (PMID 34067520, 2021). "Moreover, the transferred EV gDNA has pathophysiological significance, as a BCR/ABL hybrid gene involved in the pathogenesis of leukemia could be transferred from leukemia cells to human embryonic kidney cells or neutrophils through EVs." (PMID 34359729, 2021). "Hence, one can speculate that the BCR-ABL fusion may render leukemia cells receptive to survival signals, which could also be derived from the CNS niche." (PMID 31970588, 2020). "Treatment of BCR-ABL+ human leukemia has been significantly improved by ABL tyrosine kinase inhibitors (TKIs), but they are not curative for most patients and relapses are frequently associated with BCR-ABL mutations, warranting new targets for improved treatments." (PMID 28599273, 2017). "Therefore, IGF-IR directs BCR/ABL+ leukemia cells toward the myeloid fate." (PMID 25648584, 2015). "We next assessed whether IGF-IR regulates self-renewal of BCR/ABL leukemia cells." (PMID 25648584, 2015). "Our understanding of the pathogenesis of Ph+ leukemias has improved, but several key features remain unexplained, such as the association of the m-BCR with Ph+ ALL and different responses of (m-BCR) p185BCR/ABL and (M-BCR) p210BCR/ABL-positive leukemia to TKIs." (PMID 25919613, 2015). "However, inhibition of BCR/ABL alone is unable to eradicate Ph+ leukemia." (PMID 25919613, 2015). "We next investigated whether IGF-IR was required for the induction of leukemia by BCR/ABL." (PMID 25648584, 2015). "Notably, the co-expression of p96ABL/BCR and p185ABL/BCR induced a lymphoid-like leukemia phenotype in 37% of the mice, with the majority of BM cells expressing the B220, and only few myeloid cells and associated with moderate splenomegaly (90–300mg spleen weight)." (PMID 25919613, 2015). "A recombinant yeast-based vaccine expressing the T315I-mutated BCR-ABL antigen was demonstrated to significantly reduce or eliminate BCR-ABL (T315I) leukemia cells from the peripheral blood of immunized animals and extended leukemia-free survival in a murine BCR-ABL + leukemia model." (PMID 23241263, 2012). "Our findings showed that STAT5, more particularly, STAT5a, plays a critical role in TA regulation, suggesting that inhibition of STAT5a in combination with BCR-ABL may provide an alternative approach for treatment of leukaemia, especially in patients who are resistant to tyrosine inhibitors." (PMID 22151181, 2011).